IQGAP2 (IQ motif containing GTPase activating protein 2)
Diseases named in the same sentence as IQGAP2 in open-access papers (continued):
Sharing a sentence is not in itself a finding about the gene and the disease.
breast carcinoma (continued). "IQGAP2-IQGAP1 ratio correlated negatively with phospho-ERK levels in breast cancer patients." (PMID 33846302, 2021). "The role of IQGAP2 on the other hand is still unexplored in breast cancer." (PMID 33846302, 2021). "Overall, these findings confirm that IQGAP2 regulates EMT in breast cancer cells." (PMID 33846302, 2021). "Likewise, the TCGA dataset analysis for breast cancer via Xena browser also revealed reduced transcript levels of IQGAP2 in infiltrating ductal carcinoma (fold change = -0.97)." (PMID 29073199, 2017). "IQGAP2 might be playing role in initiation in breast cancer, lung cancer and liver cancer whereas it promotes tumor progression in colorectal, brain and kidney cancer." (PMID 29073199, 2017). "This pattern was consistent regardless of subtypes across most of the cancer types, except breast cancer wherein IQGAP2 was specifically downregulated in ductal carcinoma and infiltrating ductal/ invasive ductal carcinoma but not in infiltrating lobular or mixed type breast carcinoma." (PMID 29073199, 2017). "Furthermore, reduced IQGAP2 expression leads to increased proliferation and reduced apoptosis regardless of ER status, which results in continuous tumor growth and development of breast cancer." (PMID 36831467, 2023). "The IQ motif containing GTPase activating protein 2 (IQGAP2) gene functions as a tumor suppressor, reducing the malignant properties of breast cancer cells." (PMID 39682792, 2024). "In comparison to IQGAP2, IQGAP3 is highly expressed in breast cancer tissues relative to adjacent normal tissues." (PMID 36831467, 2023). "Next, we examined the correlation between IQGAP2/phospho-ERK and IQGAP1/phospho-ERK in breast cancer tissues." (PMID 33846302, 2021). "In opposite to IQGAP2, the expression of IQGAP3 was increased from stage I to II in lung and breast cancer and, stage II to III in prostate and kidney cancer." (PMID 29073199, 2017). "A significant change was observed in transcript levels of IQGAP2 and IQGAP3 in breast cancer compared to normal tissue, in different datasets of Oncomine." (PMID 29073199, 2017). "Kaplan-Meier analysis showed that in breast cancer, higher levels of IQGAP3 expression and lower levels of IQGAP2 expression correlate with poor survival of the patient." (PMID 29073199, 2017). "Filopodia and lamellipodia formation are considered as highly aggressive phenotypes in breast cancer, and whether IQGAP1 and IQGAP2 are correlated with the formation of filopodia and lamellipodia was unclear." (PMID 36209218, 2022). "As corroboration, we observed a strong negative correlation between IQGAP1 and IQGAP2 in breast cancer tissues." (PMID 33846302, 2021). "Unlike IQGAP1 and IQGAP3, which function as oncogenes in breast cancer, the role of IQGAP2 is still unexplored." (PMID 33846302, 2021). "Additionally, IQGAP2 inhibits EMT and angiogenesis and promotes apoptosis in breast cancer." (PMID 35785216, 2022). "In search of the mechanism, we could establish that IQGAP2 promotes apoptosis irrespective of the molecular subtype of breast cancer cells by activating the ROS-P38 pathway." (PMID 33846302, 2021). "We found that IQGAP2 depletion in breast cancer lines did not affect AKT activation." (PMID 33846302, 2021). "A strong negative correlation between IQGAP2/phospho-ERK and a positive but non-significant correlation between IQGAP1/phospho-ERK were observed in breast cancer patients." (PMID 33846302, 2021).
ovarian carcinoma (9 papers, 2017 to 2025). A malignant neoplasm originating from the surface ovarian epithelium. "The loss of IQGAP2 protein has been observed in many cancer types and is linked to prognosis, including breast, gastric, and ovarian cancers." (PMID 36362301, 2022). "Furthermore, IQGAP2 protein level is found to be down-regulated in patients with ovarian cancer and is negatively correlated with progression and survival of patients thus implicated as a biomarker for ovarian cancer." (PMID 34943212, 2021). "A similar effect was found in ovarian cancer, where IQGAP2 strongly inhibited the expression and nuclear translocation of β-catenin." (PMID 36831467, 2023). "IQGAP2 was reported to inhibit ovarian cancer cell EMT, migration along with infiltration by suppressing the Wnt-induced nuclear translocation of β-catenin, as well as transcription." (PMID 34689136, 2021). "An inverse correlation between IQGAP2 DNA methylation and mRNA expression was observed in ovarian cancer as well." (PMID 29073199, 2017). "Notably, IQGAP2 inhibited the Wnt3a-induced transcriptional activity of β-catenin in ovarian cancer, indicating that it is a suppressor of Wnt signaling." (PMID 36831467, 2023). "Likewise for IQGAP2 previous studies have identified its role as a tumor suppressor in ovarian cancer wherein reduced levels of IQGAP2 correlated with poor overall survival of patients and IQGAP2 inhibited EMT, migration and invasion." (PMID 29073199, 2017). "Further analysis proved that IQGAP2 inhibited the migration, invasion, and EMT of ovarian cancer cells through deactivation of Wnt/-catenin signaling." (PMID 36831467, 2023).
liver cancer (7 papers, 2010 to 2022). An epithelial or non-epithelial malignant neoplasm that arises from the liver. "The loss of IQGAP2 in mice spontaneously leads to liver cancer development, which is also IQGAP1-dependent." (PMID 34439095, 2021). "Researchers have suggested that IQGAP1 is oncogenic, and its upregulation leads to the induction of liver cancer, while IQGAP2 acts as a suppressor gene." (PMID 36276098, 2022). "Our study shows that IQGAP2 mRNA levels are increased in liver cancer cell lines compared to those in glioma, lung, and kidney cancer cell lines, which is consistent with previous reports." (PMID 34034707, 2021). "We showed that a reciprocal relationship existed between IQGAP1 and IQGAP2 expression in human liver cancer cell lines." (PMID 20977743, 2010). "We determined the relative amounts of IQGAP1 and IQGAP2 in a panel of human liver cancer cell lines." (PMID 20977743, 2010). "We have shown that IQGAP2 expression is downregulated in more invasive and metastatic liver cancer cell lines and most human HCC tissue." (PMID 20977743, 2010). "Remarkably, deregulation of IQGAP2 and IQGGAP3 have also been associated with liver cancer." (PMID 33672268, 2021). "Briefly, levels of IQGAP1 are commonly increased while IQGAP2 levels are decreased in liver cancer." (PMID 34439095, 2021). "Both IQGAP1 and the related protein IQGAP2 significantly impact the development of liver cancer." (PMID 34439095, 2021). "The role of IQGAP1 and IQGAP2 in liver cancer has been reviewed previously." (PMID 34439095, 2021). "IQGAP1 and IQGAP2 expression was reciprocally altered in 6/6 liver cancer cell lines." (PMID 20977743, 2010). "In TCGA database, the liver cancer TCGA dataset (LIHC-TCGA) showed low expression of IQGAP2 (fold change = -1.02) and high expression of IQGAP3 (fold change = 4.19) in liver cancer tissues, compared to the normal tissues." (PMID 29073199, 2017). "Despite this, we found that cell lines derived from haematologic malignancies exhibit higher IQGAP2 levels than liver cancer cell lines, which does not occur for IQGAP1 and IQGAP3." (PMID 34034707, 2021). "While IQGAP2 and -3 expression is restricted to specific organs, IQGAP1 is ubiquitously expressed and has been shown to be deregulated in different tumour types such as liver cancer, where it behaves as a putative oncogene." (PMID 33672268, 2021). "Immunostaining of IQGAP1 and IQGAP2 may aid in the diagnosis of HCC, and their pharmacologic modulation may represent a novel therapeutic strategy for the treatment of liver cancer." (PMID 20977743, 2010).
colorectal cancer (5 papers, 2015 to 2024). A primary or metastatic malignant neoplasm that affects the colon or rectum. "In the last decade, IQGAP2 was reported to be found in cancer tissues of prostate, lung, breast, liver, kidney, and colorectal cancer." (PMID 34034707, 2021). "In colorectal cancer only 1.9% tumor samples showed strong staining for IQGAP2, compared to 78.2% of uninvolved tissue." (PMID 29073199, 2017). "Oncomine database search for colorectal cancer showed 17 significant unique analyses with reduced IQGAP2 expression and two such unique analyses for IQGAP3 with increased mRNA expression." (PMID 29073199, 2017). "Notably, NPM1 facilitated the activation of AKT signaling in colorectal cancer, while IQGAP2 could also influence the activation of the AKT pathway." (PMID 39039052, 2024). "In contrast to IQGAP2, significantly higher expression of IQGAP3 was found in rectal mucinous adenocarcinoma (fold change = 2.38) and colorectal carcinoma (fold change = 2.58), compared to the normal tissue." (PMID 29073199, 2017). "To gain further insight into IQGAP2 expression in human IBD and colorectal cancer (CRC), we conducted an extensive meta-analysis of published RNA microarray datasets." (PMID 26047140, 2015). "In the absence of availability of any survival data for colorectal cancer in Kaplain Meier plotter, SurvExpress database was used to ascertain the prognostic value of IQGAP2 and IQGAP3 in this cancer." (PMID 29073199, 2017). "The mechanism of IQGAP2 was not analyzed in detail in colorectal cancer (CRC)." (PMID 36831467, 2023).
bladder cancer (4 papers, 2017 to 2023). "We investigated whether the expression of IQGAP2 was associated with the cell growth activity of bladder cancer cells." (PMID 36362301, 2022). "Bioinformatic analysis using TCGA and published data showed reduced IQGAP2 in bladder cancer tissue compared with normal tissue." (PMID 36831467, 2023). "We also observed decreased IQGAP2 mRNA and protein in bladder cancer cell lines compared with normal urothelium cell lines." (PMID 36831467, 2023). "In this study, we prove the tumor-suppressing role and identify the molecular mechanism of IQGAP2 in bladder cancer." (PMID 36362301, 2022). "In the majority of tumor entities, as well as in bladder cancer, IQGAP2 was expressed significantly lower in tumor tissue." (PMID 36362301, 2022). "To investigate the potential role of IQGAP2 in bladder cancer patients, we first analyzed the mRNA expression level of IQGAP2 using the Oncomine database." (PMID 36362301, 2022). "In this investigation, we found that silencing IQGAP2 increased IL-6 and CCL2 levels in bladder cancer cells, whereas the overexpression of IQGAP2 lowered IL-6, IL-8, and CCL2 levels." (PMID 36362301, 2022). "While silencing IQGAP2 facilitated the migration and invasion of bladder cancer cell lines, ectopic IQGAP2 had the reverse effect." (PMID 36362301, 2022). "To determine if the growth inhibition effect of IQGAP2 on bladder cancer cells was also a result of apoptosis, we stained cells with PI and Annexin V and performed a FACS analysis." (PMID 36362301, 2022). "The qPCR results indicate that bladder cancer cells had a significantly lower amount of IQGAP2 mRNA than the normal urothelial cell line of SV-HUC-1." (PMID 36362301, 2022). "The results from public databases indicated that the amount of IQGAP2 mRNA was significantly reduced in most cancers, including bladder cancer." (PMID 36362301, 2022). "We next used an xCELLigence RTCA System to monitor the effect of IQGAP2 on the migration and invasion activities of bladder cancer cells in real time." (PMID 36362301, 2022). "Our in vitro data clearly demonstrated that IQGAP2 had an antiproliferative effect in bladder cancer cells, which is comparable with previous findings in other cancer types." (PMID 36362301, 2022). "In conclusion, we suggest that IQGAP2 plays a tumor-suppressing role in bladder cancer, possibly via inhibiting the MAPK/ERK pathway and reducing cytokines." (PMID 36362301, 2022). "As expected, the IQGAP2 protein was relatively higher-expressed in SV-HUC-1 compared with bladder cancer cell lines." (PMID 36362301, 2022). "Overall, IQGAP2 seemed to be very weakly expressed in the urothelium, as well as in bladder cancer cells." (PMID 36362301, 2022). "Further investigation of the EMT markers E-cadherin and MMP9 indicated decreased IQGAP2-induced EMT in bladder cancer cells." (PMID 36362301, 2022). "The dysregulation of IQGAP2 is becoming increasingly evident in most tumor entities, and it plays a role in multiple oncogenic pathways, so we evaluated the role of IQGAP2 in bladder cancer." (PMID 36362301, 2022). "Lastly, we examined the expressions of IQGAP2 mRNA and protein in one normal urothelial cell line and four bladder cancer cell lines of T24, Cal29, TCCSup, and RT4 through our own analysis." (PMID 36362301, 2022). "In a recent study, we conducted research on IQGAP2 in bladder cancer for the first time." (PMID 36831467, 2023). "Then, we analyzed the functional role of IQGAP2 in bladder cancer cells." (PMID 36831467, 2023). "However, we showed that IQGAP2 acted as a tumor suppressor by the inhibition of growth, migration, and invasion in bladder cancer cells, probably through the regulation of the MAPK/ERK pathway and cytokines, although it is not known how IQGAP2 is regulated." (PMID 36362301, 2022). "This study initially showed that IQGAP2 was reduced in bladder cancer cells." (PMID 36362301, 2022). "Reduced IQGAP2 promoted EMT in bladder cancer cells via activation of the MAPK/ERK pathway." (PMID 36362301, 2022).
bladder cancer (continued). "IQGAP2 effectively attenuated bladder cancer cell growth independently from apoptosis." (PMID 36362301, 2022). "Moreover, an in vitro analysis indicated that IQGAP2 acted as a tumor suppressor in bladder cancer through the inhibition of tumor growth, migration, and invasiveness." (PMID 36362301, 2022). "However, the role of IQGAP2 in bladder cancer is still unclear." (PMID 36362301, 2022). "We suggest that cytokine expression could be suppressed by IQGAP2 in bladder cancer cells." (PMID 36362301, 2022). "In this study, we detected IQGAP2 expression in MIBC and early NMIBC samples from the same patients and then revealed the role of IQGAP2, a known tumor suppressor, in bladder cancer progression." (PMID 36362301, 2022).
diabetes (4 papers, 2016 to 2025). "Further, MFHAS1 and IQGAP2 have some known association with diabetes or related disorders, whereas the other three genes: ZMYM3, HSD17B10 and ABCB7 have no known direct association with diabetes." (PMID 41462339, 2025). "Other genes in the SB network related to diabetes are PTP4A2, IQGAP2, and SOCS4." (PMID 26830357, 2016).
kidney cancer (4 papers, 2017 to 2021). Primary or metastatic malignant neoplasm involving the kidney. "Our results verify that IQGAP2 mRNA expression is correlated with the overall survival of patients with hepatocellular and kidney carcinoma." (PMID 34034707, 2021). "The mRNA expression of IQGAP2 and IQGAP3 was analysed among different cancer stages (I to IV) in lung, breast, stomach, colorectal, prostate, liver and kidney cancer, whereas the expression in brain cancer was compared between the histologic grades (G2 and G3) because of the lack of stage wise data." (PMID 29073199, 2017).
colitis (3 papers, 2015 to 2021). Inflammation of the colon. "Mechanistically, resistance to colitis was associated with suppression of colonic NF-κB signaling and IL-6 synthesis, along with diminished neutrophil and macrophage production and recruitment in Iqgap2-/- mice." (PMID 26047140, 2015). "Overall colitis clinical score was determined at 10 ± 1.8 for WT mice (with 12 being the maximal possible score) and 0.6 ± 0.7 for Iqgap2-/- mice, indicating severe colitis in WT and its absence in Iqgap2-/- mice." (PMID 26047140, 2015). "Unchanged or even modestly decreased levels of Iqgap2 RNA transcript observed in human colitis specimens can be interpreted as follows." (PMID 26047140, 2015). "Protection from colitis in Iqgap2-/- mice was evident by maintenance of normal body weight, absence of hematochezia and intact colonic epithelium and crypt architecture." (PMID 26047140, 2015). "Overall, Iqgap2-/- mice displayed significant resistance to DSS-induced colitis as evident by maintenance of a normal body weight, intact colonic morphology and lack of clinical symptoms." (PMID 26047140, 2015). "Here we show for the first time that ablation of the Iqgap2 gene leads to protection from dextran sulfate sodium (DSS)-induced colitis in mice." (PMID 26047140, 2015). "We found that Iqgap2-/- mice were protected from colonic injury in the DSS-induced colitis model." (PMID 26047140, 2015). "Our results show that IQGAP2 may be capable of both: aiding the development of colitis through a direct function in colonic epithelium and in a more indirect manner, through modifying neutrophil/macrophage maturation, their inflammatory recruitment and migration, and overall innate immune response." (PMID 26047140, 2015). "CBCs of Iqgap2-/- mice, IQGAP2 protein expression pattern observed in human colitis biopsy specimens and data on the conditional deletion of Rac1 in mouse neutrophils and macrophages suggest that the neutrophil/macrophage axis may be the predominant one in IQGAP2’s pro-inflammatory function." (PMID 26047140, 2015). "It has been reported that mice lacking IQGAP2 are resistant to chemically induced colitis and experience diminished neutrophil and macrophage production and recruitment." (PMID 34034707, 2021). "WT colons displayed intense nuclear pSTAT3 staining in areas of epithelial damage from DSS-induced colitis and, unlike Iqgap2-/- colons, in the stroma." (PMID 26047140, 2015). "This suggests the possibility of an earlier unexplored defect in immune cell maturation in Iqgap2-/- mice, which also could explain their protection against DSS-induced colitis." (PMID 26047140, 2015). "It was shown that azoxymethane (AOM)-DSS-induced colitis triggered up-regulation of Iqgap2 expression in MyD88-/- colons and not in the similarly treated WT controls, suggesting that MyD88 or its downstream effectors may negatively regulate IQGAP2 expression." (PMID 26047140, 2015). "Mice lacking Iqgap2 gene (Iqgap2-/- mice) were resistant to chemically-induced colitis." (PMID 26047140, 2015).
lymphoma (3 papers, 2017 to 2023). A malignant (clonal) proliferation of B- lymphocytes or T- lymphocytes which involves the lymph nodes, bone marrow and/or extranodal sites. "Only in lymphoma did DLBCL patients with a higher expression of IQGAP2 have a worse prognosis, and IQGAP3 overexpression was correlated with an excellent prognosis." (PMID 36831467, 2023). "Furthermore, high-grade lymphoma expressed higher IQGAP2 protein levels than low-grade lymphoma, indicating that IQGAP2 is related to the malignancy of DLBCL." (PMID 36831467, 2023).
astrocytoma (2 papers, 2017 to 2019). "The TCGA brain cancer datasets (GBM, LGG and GBMLGG) also showed higher expression of IQGAP2 in glioblastoma (fold change = 4.80), astrocytoma (fold change = 3.55), oligodendroglioma (fold change = 2.54) and oligoastrocytoma (fold change = 2.80)." (PMID 29073199, 2017).
Breast Invasive Carcinoma (2 papers, 2021 to 2025). "We analyzed Breast Invasive Carcinoma, TCGA, Firehose Legacy data and observed a negative correlation between MAPK1_PY187 and IQGAP2, whereas a non-significant but positive correlation was observed between MAPK1_PY187 and IQGAP1." (PMID 33846302, 2021).
gastric tumor (2 papers, 2012 to 2017). "Similarly, 17% of stomach tumor cases showed strong staining for IQGAP2, in comparison to 95.56% of uninvolved tissue samples." (PMID 29073199, 2017).
hearing loss (2 papers, 2012 to 2021). "We observed that several SNPs in SCARNA16, IQGAP2, PTPRK, GLI3, ADARB2 and NDUFV2, which have been reported to be significantly associated with several other types of hearing loss, were also significantly associated with NIHL in this study (all P values ≤ 0.05)." (PMID 33242228, 2021).